SLC17A3 (solute carrier family 17 member 3)
Description:
Mediates the renal excretion of uremic toxin 3-indoxyl sulfate. [Isoform 2]: Transports organic anions in a voltage-driven, multispecific, manner, on the apical side of renal proximal tubule. In particular, participates in the secretion of urate from the cell into the lumen. Urate is the end product of purine metabolism. May have roles in the metabolism and secretion of estrone sulfate, estradiol-17-beta-glucuronide, ochratoxin A, as wells as drugs such as bumetanide.
Synonyms: NPT4; GOUT4; UAQTL4
Tractability: Antibody: UniProt places it where antibodies can reach, with high confidence; its Gene Ontology location is reachable by antibodies, with high confidence; UniProt predicts a signal peptide or a membrane-spanning region.
Gene: Protein-coding gene on chromosome 6 (25,833,066 to 25,882,478, reverse strand). Ensembl gene ENSG00000124564.
Subcellular location: Endoplasmic reticulum membrane (Isoform 1); Cell membrane (Isoform 2)
Pathways (Reactome):
Transport of small molecules: Stimuli-sensing channels
Gene Ontology:
Molecular function: efflux transmembrane transporter activity; toxin transmembrane transporter activity; transmembrane transporter activity; urate transmembrane transporter activity; voltage-gated monoatomic anion channel activity; xenobiotic transmembrane transporter activity; sodium:phosphate symporter activity
Biological process: transmembrane transport; urate metabolic process; urate transport; xenobiotic detoxification by transmembrane export across the plasma membrane; glucose-6-phosphate transport; monoatomic ion transmembrane transport; phosphate ion transport; sodium ion transport; monoatomic anion transmembrane transport; sodium ion transmembrane transport
Cellular component: apical plasma membrane; cytoplasm; endoplasmic reticulum membrane; perinuclear region of cytoplasm; plasma membrane; brush border membrane
Genetic constraint (gnomAD): Loss-of-function variants: 53 observed, 56.43 expected, observed/expected ratio (o/e) 0.94, 90% interval 0.75 to 1.18. The upper end of that interval is the gene's LOEUF score, 1.18, which puts it in group 5 of 6, group 1 being the genes least tolerant of losing a copy. Missense variants: 608 observed, 604.16 expected, observed/expected ratio (o/e) 1.01, 90% interval 0.94 to 1.08. Synonymous variants: 187 observed, 215.13 expected, observed/expected ratio (o/e) 0.87, 90% interval 0.77 to 0.98.
Homologues: Orthologues: chimpanzee SLC17A3 (99% identical), macaque SLC17A3 (93% identical), pig SLC17A3 (71% identical), mouse Slc17a3 (65% identical), rat Slc17a3 (65% identical), dog SLC17A3 (56% identical), zebrafish si:ch1073-513e17.1 (34% identical), zebrafish slc17a5 (33% identical), Drosophila melanogaster MFS14 (28% identical), Drosophila melanogaster Picot (27% identical), Caenorhabditis elegans slc-17.2 (27% identical), Drosophila melanogaster CG2003 (27% identical), and 44 more. Paralogues in human: SLC17A2 (53% identical), SLC17A4 (52% identical), SLC17A1 (45% identical), SLC17A5 (32% identical), SLC17A8 (30% identical), SLC17A6 (29% identical), SLC17A7 (28% identical), SLC17A9 (20% identical), SLC37A1 (16% identical), SLC37A2 (15% identical), SLC37A4 (14% identical), SLC37A3 (13% identical).
Diseases named in the same sentence as SLC17A3 in open-access papers:
SLC17A3 is named in the same sentence as 24 diseases in open-access papers, as found by Europe PMC text mining. Sharing a sentence is not in itself a finding about the gene and the disease. The quoted sentences say what the papers report.
gout (7 papers, 2009 to 2024). A condition characterized by painful swelling of the joints, which is caused by deposition of urate crystals. "Global genome-wide association studies indicated that SLC17A1 rs1165196 and other variants from SLC17A3 are associated with uric acid concentrations and gout." (PMID 37696853, 2023). "This large window in chromosome 6 (56 SNPs) had a strong, positive significant covariance signal and SLC17A1 and SLC17A3 are urate transporters both linked to gout." (PMID 35876900, 2022). "Marker rs1165205 in SLC17A3 was first associated with gout (OR = 0.85, P = 0.002)." (PMID 22541845, 2012). "Another SNP marker, rs1165205 in SLC17A3, which is in strong LD with rs1183201 in SLC17A1 was previously found to be related to serum UA levels and also representing a risk factor for gout." (PMID 19890391, 2009). "None of the variants of the known gout and hyperuricemia-related genes were co-segregated with the disease phenotype in this family, including ABCG2, SLC2A9, SLC22A11, SLC22A12, SLC17A1, SLC17A3, PDZK1, and INHBB." (PMID 39433541, 2024).
hyperuricemia (4 papers, 2020 to 2024). An abnormally high level of uric acid. "The in vivo role of NPT4 is supported by the presence of missense mutations (N68H and F304S) in SLC17A3 in underexcretion-type hyperuricemia patients." (PMID 36483739, 2022). "Loss of function mutations in SLC17A3 have been shown to result in hyperuricemia therefore, hypermethylation at these regions may result in elevated blood uric acid levels, which is consistent with elevated levels of uric acid levels seen in individuals with CD." (PMID 32014011, 2020).
essential hypertension (2 papers, 2018 to 2022). Hypertension that presents without an identifiable cause. "Besides, traits association analysis showed that 3 SNPs (rs62394289 in the SLC17A3 gene, rs9378220 in TRIM31, rs112733823 in LINC00243) were associated with other potential risk factors of stroke (high blood pressure and Rheumatoid arthritis) and therefore, were also excluded." (PMID 36741373, 2022).
kidney cancer (2 papers, 2021 to 2022). Primary or metastatic malignant neoplasm involving the kidney. "Because the primary lesion and lymph node metastasis of HLRCC-associated kidney cancer were clustered in different clusters, we investigated their differentially expressed genes and found that the expression of SLC17A3—a proximal tubule marker—was lost in the lymph node metastasis." (PMID 35874919, 2022). "The lymph node metastasis completely lost expression of SLC17A3, a proximal tubule marker, suggesting that the hypermethylation of CpG islands in HLRCC-associated kidney cancer may further affect gene expressions to adapt to the lymph node tissue microenvironment." (PMID 35874919, 2022). "In particular, ELF5, SLC17A3, RALBP1, WNK1, APOC1, and CRYAB were experimentally verified to play an important role in the occurrence and development of kidney cancer." (PMID 34445498, 2021).
Nephropathy (2 papers, 2021 to 2023). A nonspecific term referring to disease or damage of the kidneys. "Tag-SNPs captured by SLC17A3 rs942379 variant additionally impacts the expression of BTN3A2 in glomerulus and those captured by TATDN2 rs394558 variant combinedly affects the expression of ATP2B2 in glomerulus further elucidating its role in nephropathy related traits." (PMID 37696853, 2023).
metabolic disorders (1 paper, 2022). "SLC17A3 is a voltage-driven transporter of intracellular urate and organic anions from blood into renal tubular epithelial cells, and it thus plays an important role in metabolic disorders including serum uric acid concentration." (PMID 36077407, 2022).
nephrolithiasis (1 paper, 2014). The presence of a calculus in the pelvis of the kidney; this is most often composed of mineral salts and proteins. "Additional factors, such as sequence variation in other UA transporters (SLC22A12, SLC17A3, ABCC4 and ABCG2), age, sex, diet, drugs, physical activity, environment and volume status can influence the degree of UA tubular absorption and the risk of EIARF or nephrolithiasis." (PMID 24397858, 2014).
Obesity (1 paper, 2025). Accumulation of substantial excess body fat. "Furthermore, obesity led to the up-regulation of sodium transporters (Slc13a1, Slc22a8, Slc17a1, Slc17a3) and the down-regulation of structural proteins (Col4a3, Col4a4) as well as Na/K-ATPase subunits encoded by Atp1a1, Atp1b1, suggesting impaired sodium metabolism and underlying renal injury." (PMID 41133844, 2025).
systemic lupus erythematosus (1 paper, 2025). An autoimmune multi-organ disease typically associated with vasculopathy and autoantibody production. "Among the 127 likely pathogenic terms associated with those 68 SLCs (Fig. EV2C), we found systemic lupus erythematosus (SLE) associated with SLC15A2, SLC15A4, and SLC17A3." (PMID 40355757, 2025).
tumor (3 papers, 2021 to 2025). "The cell type-specific markers we used for cell annotation were as follows: T cell (CD3D); NK cell (KLRD1 and NKG7); plasma cell (IGKC and JCHAIN); Mast cell (KIT and TPSB2); tumour cell (CA9, NDUFA4L2 and SLC17A3); endothelium (PECAM1, PTPRB and KDR); mesangial cell (ACTA2 and PDGFRB)." (PMID 40830065, 2025).
disorders of iron metabolism (2 papers, 2018 to 2022). "We also identified 18 novel genotype–phenotype associations (at the PheWAS threshold of P<8.57e-05), of which the association between rs1165151 (SLC17A3 locus) and disorders of iron metabolism had the smallest P value (P=1.23e-19)." (PMID 29437585, 2018).
SLC17A3 also shares sentences with these, for which no sentence is quoted: cancer (1 paper); cholestasis (1); clear cell renal cell carcinoma (1); coeliac disease (1); diabetic kidney disease (1); hypercholesterolaemia (1); phospholipidosis (1); Renal cyst (1); rheumatoid arthritis (1); steatosis (1); Stroke (1); type 1 diabetes (1); Type 2 Diabetes (1).